ACP3 (acid phosphatase 3)
Description:
A non-specific tyrosine phosphatase that dephosphorylates a diverse number of substrates under acidic conditions (pH 4-6) including alkyl, aryl, and acyl orthophosphate monoesters and phosphorylated proteins. Has lipid phosphatase activity and inactivates lysophosphatidic acid in seminal plasma. [Isoform 2]: Tyrosine phosphatase that acts as a tumor suppressor of prostate cancer through dephosphorylation of ERBB2 and deactivation of MAPK-mediated signaling. In addition to its tyrosine phosphatase activity has ecto-5'-nucleotidase activity in dorsal root ganglion (DRG) neurons. Generates adenosine from AMP which acts as a pain suppressor (By similarity). [PAPf39]: (Microbial infection) Forms amyloid beta-sheet fibrils in semen. These fibrils, termed SEVI (semen-derived enhancer of viral infection) capture HIV virions, attach them to target cells and enhance infection. SEVI amyloid fibrils are degraded by polyphenol epigallocatechin-3-gallate (EGCG), a constituent of green tea. Assembly of SEVI amyloid fibrils and their amplification of HIV infection is inhibited by WW61, a non-natural hexapeptide inhibitor (Trp-His-Lys-chAla-Trp-hydroxyTic). The target cell attachment and enhancement of HIV infection is also inhibited by surfen. Also similarly boosts XMRV (xenotropic murine leukemia virus-related virus) infection.
Synonyms: PAP; 5'-NT; ACPP; ACP-3; TM-PAP
Tractability: Small molecule: a structure with a bound ligand is known; a high-quality ligand is known; it has a binding pocket of medium quality; it belongs to a druggable protein family. Antibody: UniProt places it where antibodies can reach, with high confidence; its Gene Ontology location is reachable by antibodies, with high confidence; UniProt predicts a signal peptide or a membrane-spanning region. PROTAC: a small molecule that binds it is known. Other modalities: an approved drug acts on it.
Target class: Enzyme; Phosphatase
Gene: Protein-coding gene on chromosome 3 (132,317,369 to 132,368,302, forward strand). Ensembl gene ENSG00000014257.
Subcellular location: Secreted (Isoform 1); Cell membrane (Isoform 2); Lysosome membrane; Nucleus; Cytoplasm, cytosol
Pathways (Reactome):
Immune System: Neutrophil degranulation
Gene Ontology:
Molecular function: 5'-nucleotidase activity; acid phosphatase activity; identical protein binding; lysophosphatidic acid phosphatase activity; molecular adaptor activity; phosphatase activity; protein binding; protein homodimerization activity; protein tyrosine phosphatase activity; thiamine phosphate phosphatase activity; choline binding
Biological process: adenosine metabolic process; positive regulation of adenosine receptor signaling pathway; regulation of sensory perception of pain; thiamine metabolic process; nucleotide metabolic process; purine nucleobase metabolic process
Cellular component: extracellular exosome; extracellular region; lysosomal membrane; nucleus; plasma membrane; azurophil granule membrane; vesicle membrane; apical part of cell; cytosol; filopodium; Golgi cisterna; membrane; multivesicular body; secretory granule
Genetic constraint (gnomAD): Loss-of-function variants: 24 observed, 31.29 expected, observed/expected ratio (o/e) 0.77, 90% interval 0.56 to 1.08. The upper end of that interval is the gene's LOEUF score, 1.08, which puts it in group 4 of 6, group 1 being the genes least tolerant of losing a copy. Missense variants: 335 observed, 355.52 expected, observed/expected ratio (o/e) 0.94, 90% interval 0.86 to 1.03. Synonymous variants: 123 observed, 132.26 expected, observed/expected ratio (o/e) 0.93, 90% interval 0.8 to 1.08.
Homologues: Orthologues: chimpanzee ACP3 (98% identical), macaque ACP3 (92% identical), rabbit ACP3 (83% identical), pig ACP3 (82% identical), dog ACP3 (81% identical), mouse Acp3 (80% identical), rat Acp3 (79% identical), guinea pig ACP3 (75% identical), tropical clawed frog acp3 (49% identical), Drosophila melanogaster Acph-1 (35% identical), Drosophila melanogaster CG9449 (32% identical), Caenorhabditis elegans pho-5 (30% identical), and 13 more. Paralogues in human: ACP2 (48% identical), ACP4 (40% identical), ACP6 (26% identical), PXYLP1 (22% identical), FRA10AC1 (12% identical).
Diseases named in the same sentence as ACP3 in open-access papers:
ACP3 is named in the same sentence as 43 diseases in open-access papers, as found by Europe PMC text mining. Sharing a sentence is not in itself a finding about the gene and the disease. The quoted sentences say what the papers report.
prostate carcinoma (106 papers, 2003 to 2025). A carcinoma that arises from epithelial cells of the prostate gland. "In contrast, we observed minimal differences in the levels of prostate and prostate cancer-associated proteins, including KLKB1, KLK2, KLK3, ACP3, and SLC45A3, which are markers of conventional adenocarcinoma of the prostate." (PMID 39910169, 2025). "Given the high and selective expression of ACP3 in prostate cancer lesions, the use of S‐A2855/B725 as tumor‐targeting moiety may lead to the development of radioligand theranostics for PCa with low uptake in salivary glands and kidney." (PMID 40583265, 2025). "ACP3 is a prostatic acid phosphatase that also regulates prostate cancer cell growth by dephosphorylating ERBB2, which is a part of the adjacent network of our target gene CHST2 in our previous study that shows a slight negative correlation with TPS and deactivates MAPK-mediated signalling." (PMID 39457550, 2024).
Buruli ulcer (1 paper, 2018). "More than 80% of patients and contacts from endemic areas produced IFN-γ in response to all the antigens except acyl carrier protein type 3 (ACP3) to which only 47% of active Buruli ulcer cases and 71% of contacts responded." (PMID 30090691, 2018). "Using a cut off of 37 pg/ml of IFN-γ to define a responder status, more than 80% of patients and contacts from endemic areas responded to all the antigens except ACP3 to which only 47% of active Buruli ulcer cases and 71% of contacts responded." (PMID 30090691, 2018).
tumor (48 papers, 2007 to 2025). "We speculated that CNA events affecting different ACP3 neighbors might be in operation in different tumor specimens." (PMID 33317623, 2020). "This accords with significantly increased ADC values in ACP2 derived xenografts relative to ACP1 and ACP3 PDX, and higher average vital tumor content." (PMID 29795641, 2018). "In concordance with the histologically assessed tumor vitality, varying on average between <10% (ACP1, n = 7), ~41% (ACP2, n = 10) and ~26% (ACP3, n = 10), the T2 volume of ACP2 differs significantly from ACP1 and ACP3." (PMID 29795641, 2018).
cancer (41 papers, 2006 to 2025). A tumor composed of atypical neoplastic, often pleomorphic cells that invade other tissues. "These libraries were screened in parallel against CAIX, PSMA, ACP3, NKG2D, and closely related protein targets to discover highly specific and potent ligands for cancer treatment and immunotherapy." (PMID 40583265, 2025).
infection (6 papers, 2010 to 2026). The state of being infected such as from the introduction of a foreign agent such as serum, vaccine, antigenic substance or organism. "In particular, the 18-fold increase in expression of acp3 in an acute infection model and 30-fold increase in a chronic infection model strongly suggests a key role for Acp3 in pathogenicity." (PMID 30294316, 2018). "By contrast, when tested in a mouse infection model, a 1000-fold increase in bacterial load was detected for both acp1 and acp3 deletion mutants, indicating that both Acp1 and Acp3 play a role in P. aeruginosa pathogenicity in vivo." (PMID 30294316, 2018). "Previous studies have showed that acp1 and acp3 expression is regulated by quorum sensing (QS) and acp3 is highly induced during infection." (PMID 30294316, 2018). "One reason for the higher persistence of the acp3 mutant in the mouse infection model could be increased tolerance to reaction oxygen species (ROS) related to the binding of Acp3 with KatA and potential influence on its activity." (PMID 30294316, 2018). "Deletion of acp3 from P. aeruginosa strain PAO1 results in thicker biofilm formation, increased resistance of the strain to hydrogen peroxide, and higher persistence in a mouse infection model." (PMID 30294316, 2018).
ACP3 also shares sentences with these, for which no sentence is quoted: metastatic prostate carcinoma (10 papers); prostate adenocarcinoma (9); breast carcinoma (5); prostate tumor (5); viral infection (4); benign prostatic hyperplasia (3); prostatitis (3); adenocarcinoma (2); colorectal cancer (2); lung carcinoma (2); schizophrenia (2); AIDS (1); bipolar disorder (1); bladder cancer (1); bone metastasis (1); breast cyst (1); Carcinoid tumours (1); esophageal cancer (1); glioblastoma (1); heart failure (1); HIV-1 infection (1); infertile (1); kidney cancer (1); kidney tumor (1); lung adenocarcinoma (1); male infertility (1); melanoma (1); mental disorder (1); metastatic disease (1); osteoporosis (1).
A further 8 diseases each share a sentence with ACP3 in 1 paper.